METTL3 (methyltransferase 3, N6-adenosine-methyltransferase complex catalytic subunit)
Diseases named in the same sentence as METTL3 in open-access papers (continued):
Sharing a sentence is not in itself a finding about the gene and the disease.
prostate carcinoma (66 papers, 2020 to 2026). A carcinoma that arises from epithelial cells of the prostate gland. "The authors proposed that downregulation of METTL3 may result in a transformation of prostate cancer-associated macrophages from M1-like pro-inflammatory to M2-like anti-inflammatory type." (PMID 40862723, 2025). "Therefore, METTL3 plays an oncogenic role in prostate cancer and may be used in combination with PSA as a diagnostic marker for this disease." (PMID 32765970, 2020). "In lung cancer, the USP35 deubiquitination modification inhibits the proteasome-mediated degradation pathway, whereas in prostate cancer, METTL3 stabilizes RRBP1 through m6A modification." (PMID 41200062, 2026). "In summary, RRBP1 is a core effector molecule of the METTL3/m6A signaling axis in prostate cancer and its m6A-dependent stabilization promotes tumor aggressiveness and is closely associated with poor patient prognosis." (PMID 41200062, 2026). "Another small molecule, STM2457, a METTL3 inhibitor, suppresses the proliferation, migration, and invasion of prostate cancer cells by reducing m6A methylation levels." (PMID 40830264, 2025). "METTL3 is upregulated in prostate cancer (PCa) tissues and promotes MYC expression through m6A modification, which promotes PCa cell growth and progression." (PMID 39289775, 2024). "The RNA and protein levels of METTL3 and FTO in RWPE-1, LNCaP, PC-3, 22RV1, and DU145 cells were assessed, and the results showed that METTL3 expression was up-regulated while FTO expression was down-regulated in prostate cancer cells." (PMID 38384328, 2024). "Immunohistochemistry (IHC) results showed that METTL3 was up-regulated in prostate cancer, whereas FTO was down-regulated." (PMID 38384328, 2024). "YTHDF2 mediates the mRNA degradation of the tumor suppressors LHPP and NKX3-1 in a METTL3-dependent manner to regulate AKT phosphorylation-induced prostate cancer progression." (PMID 38281945, 2024). "In the matched clinical samples, the FTO level was down-regulated and METTL3 was up-regulated in most prostate cancer samples." (PMID 38384328, 2024). "on prostate cancer revealed that METTL3 promotes the stability of lncRNA SNHG7 through an m6A modification, and this stable lncRNA accelerates glycolysis in prostate cancer through the SRSF1/c-Myc axis." (PMID 39759516, 2024). "The results showed that prostate cancer patients having higher METTL3 expression and lower FTO expression exhibited reduced disease-free survival (DFS)." (PMID 38384328, 2024). "Although the role of METTL3 has been extensively studied in many cancers, its role in isoform switching in prostate cancer (PCa) has been poorly explored." (PMID 37675218, 2023). "In vitro and in vivo experiments have confirmed that ASO targeting METTL3 can reduce the proliferation of drug-resistant prostate cancer when combined with Enzalutamine." (PMID 37095108, 2023). "In prostate cancer, the higher the expression of METTL3 and YTHDF2, the lower the survival rate of prostate cancer patients." (PMID 37701836, 2023). "Our results show that METTL3 promotes the resistance of prostate cancer cells to ADT drugs such as enzalutamide." (PMID 37095108, 2023). "In prostate cancer, the literature has confirmed that METTL3 is significantly up-regulated in cancer tissues compared to normal prostate tissues." (PMID 37095108, 2023). "Knockdown of METTL3 reduced the proliferation, migration, invasion and DNA synthesis ability of prostate cancer cells, and inhibited tumor formation and reduced lung metastasis." (PMID 37701836, 2023). "In prostate cancer, m6A modification level was upregulated, and the expression levels of METTL3, METTL14, VIRMA, RNA binding motif protein 15 (RBM15), HNRNPC, HNRNPA2B1, YTHDC2, YTHDF1 and YTHDF2 increased." (PMID 37701836, 2023). "Knockdown of Mettl3 in prostate cancer cells also increased protein expression of pro-apoptotic proteins BAK and BAX, CASP3 and CASP7 activity, and PARP cleavage." (PMID 35350378, 2022).
prostate carcinoma (continued). "In prostate cancer, the m6A writer METTL3 has been confirmed to promote the proliferation and metastasis of PCa." (PMID 35354789, 2022). "Genetic depletion and overexpression of METTL3 in various prostate cancer cell lines demonstrate that METTL3 can significantly promote the proliferation, migration and invasion of prostate cancer cells." (PMID 36008936, 2022). "A more recent finding conveyed that METTL3 was highly expressed in prostate cancer and promoted cancer cell growth and invasion through SHH-GLI1 signaling." (PMID 36360287, 2022). "METTL3 is upregulated in prostate cancer cells compared to normal cells and is a poor prognostic factor for patient survival." (PMID 36008936, 2022). "While, METTL3 has been found to be upregulated in prostate cancer, and METTL3 increases the cell proliferation and migration of prostate cancer cells by activating expression of LEF1 or Myc in an m6A methylation dependent manner." (PMID 33611339, 2021). "Other recent studies have reported that METTL3 is overexpressed in prostate cancer cells, contributing to the growth and invasion of cancer cells through SHH-GLI1 signalling." (PMID 33461542, 2021). "In conclusion, KIF3C was overexpressed in the prostate cancer and exerted as an oncogene involving in promoting proliferation and metastasis, which was regulated by METTL3 in m6A modification dependence." (PMID 34537760, 2021). "The expression of METTL3 in prostate cancer cell lines determined that it is highly expressed in prostate cancer." (PMID 34537760, 2021). "METTL3 also exhibited its regulatory effect on Hedgehog pathway promoting prostate cancer cell proliferation, survival and invasive capability." (PMID 33814008, 2021). "KIF3C was overexpressed in prostate cancer, promoting its growth migration and invasion was induced by miR-320d/METTL3 in an m6A dependent process." (PMID 34537760, 2021). "METTL3 expression is higher in prostate cancer than in normal prostate tissue, especially in prostate cancer with bone metastasis." (PMID 32765970, 2020). "In our ongoing study, we found that METTL3 in prostate cancer was up‐regulated and contributed to the carcinogenesis of prostate cancer." (PMID 32808488, 2020). "Overexpression of the m6A methyltransferase METTL3 has been reported in a variety of prostate cancer cell lines, which promotes cell proliferation, survival, and invasion." (PMID 33273988, 2020). "METTL3 is highly expressed in bladder and prostate cancer and plays an oncogenic role on cancer cells; however, its expression and role are opposite in kidney cancer." (PMID 32765970, 2020). "Knockdown of METTL3 in prostate cancer cell lines reduces the m6A content and inhibits survival, cell proliferation, colony formation, and invasion." (PMID 32765970, 2020). "Specifically, copy number loss of HNRNPC, METTL3, and FTO were significantly correlated with poor survival of prostate cancer, while patients with copy number gain of RBM15 and ALKBH5 had worse RFS." (PMID 32710725, 2020). "We found that the CNVs patterns of HNRNPC, METTL3, RBM15, ALKBH5 and FTO (one reader, two writers, and two erasers) were notably associated with RFS of prostate cancer." (PMID 32710725, 2020). "Cai et al30 also demonstrated that the METTL3 promoted proliferation and metastasis of prostate cancer." (PMID 32808488, 2020). "METTL3 protein and mRNA expression levels in prostate cancer are significantly higher than those in adjacent benign tissue." (PMID 32765970, 2020). "High METTL3 expression is positively correlated with prostate cancer progression and poor prognosis." (PMID 32765970, 2020). "For example, METTL3, as an RNA m6A methyltransferase, can promote the growth of prostate cancer by regulating the Hedgehog pathway." (PMID 33033522, 2020).
prostate carcinoma (continued). "Furthermore, RSM3 serves as a stapled peptide inhibitor for METTL3 and can induce METTL3 degradation and suppress m6A mRNA methylation, exhibiting remarkable anticancer efficacy in a prostate cancer cell xenograft tumor model." (PMID 40986143, 2025). "METTL3 facilitated prostate cancer progression by upregulating LEF1 m6A methylation." (PMID 39867638, 2025). "UZH2 is a newly synthesized small molecule METTL3 inhibitor that could reduce the level of m6A modification in prostate cancer cells." (PMID 37701836, 2023). "METTL3 has been identified as an oncogene in prostate cancer." (PMID 37095108, 2023). "Some scholars, such as Cotter, mentioned that METTL3 may have a tumor suppressor effect when prostate cancer cells transdifferentiate to NEPC." (PMID 37095108, 2023). "One study showed that knocking out METTL3 drives prostate cancer cell resistance to androgen receptor antagonists; hence, the change in m6A abundance may be a mechanism underlying treatment resistance in metastatic prostate cancer." (PMID 35945641, 2022). "METTL3 expression showed to be dramatically upregulated within prostatic carcinoma samples in comparison with normal control, according to The Cancer Genome Atlas Prostate Adenocarcinoma (TCGA-PRAD) dataset and Gene Expression Omnibus (GEO) dataset (GSE200879)." (PMID 35985997, 2022). "In addition, the protein level of PLK1 was downregulated in METTL3-KO prostate cancer cells and in cells treated with the m6A inhibitor DAA." (PMID 36439881, 2022). "Furthermore, miR-320d can inhibit KIF3C expression by targeting METTL3 to inhibit the growth and invasion of prostate cancer." (PMID 36591520, 2022). "METTL3 stabilizes ARHGDIA mRNA by modulating ELAVL1 expression in prostate cancer." (PMID 36348434, 2022). "Additionally, knockdown of Mettl3 in prostate cancer cells decreased protein expression of anti-apoptotic genes BCL-2 and BCL-XL." (PMID 35350378, 2022). "Indeed, different and sometimes contradictory results were also reported for kidney cancer concerning FTO and for METTL3 in prostate cancer." (PMID 35048498, 2022). "A recent study reported that METTL3 could stabilize ITGB1 mRNA via an m6A-HuR-dependent mechanism to promote bone metastasis in prostate cancer." (PMID 34277426, 2021). "Hence, our study aimed to explore the role of the regulatory mechanism of KIF3C, METTL3, and miR-320d in developing prostate cancer." (PMID 34537760, 2021). "Moreover, EIF4EBP1 and RPS6KB1 showed a positive correlation with the catalytic subunit METTL3 in prostate cancer and contained candidate sites for m6A modifications (Supplementary Excel S6), suggesting m6A involvement in their translation." (PMID 33273988, 2020). "METTL3 is highly expressed in bladder and prostate cancer, where it plays oncogenic role." (PMID 32765970, 2020). "Studies of METTL3 in prostate cancer suggest that it is a oncogene." (PMID 32765970, 2020). "Moreover, METTL3-mediated PTEN downregulation has shown to affect the important cancer-associated processes, the METTL3 and PTEN expression and their correlation in prostate cancer patients were analyzed based on bioinformatic analysis." (PMID 35985997, 2022). "Thus, METTL3 is involved in the regulation of multiple pathways and mechanisms in prostate cancer and may have a pivotal position in this complex regulatory network." (PMID 32765970, 2020). "A potent METTL3 selective inhibitor (UZH2, METTL3 IC50 = 5 nM) has certain inhibitory activity in the MOLM-13 cells (EC50 = 0.7 μM) and prostate cancer cells (EC50 = 2.5 μM)." (PMID 40830264, 2025). "On a mechanical level, in prostate cancer PC-3 and DU-145 cells, SNHG7 stimulated glycolysis via the SRSF1/c-MYC axis; N6-methyladenosine (m6A) modification by methyltransferase-like 3 (METTL3) boosted SNHG7 stability." (PMID 39346921, 2024). "The expression of METTL3 and METTL14 also significantly increased in castration-resistant prostate cancer." (PMID 37701836, 2023).
prostate carcinoma (continued). "Another study found that METTL3 advanced the expression of Integrin β1 (ITGB1) in a m6A-HuR-dependent manner, promoting the bone metastasis of prostate cancer cells." (PMID 36008936, 2022). "In terms of mechanisms, one study revealed that METTL3 can elevate the expression of MYC mRNA and protein levels by increasing the m6A level of the MYC transcript, which leads to carcinogenesis of prostate cancer." (PMID 36008936, 2022). "METTL3 exerted these effects by enhancing the expression of GLI1, one of the key Hedgehog signaling proteins which contributed to prostate cancer progression by upregulation of downstream targets c-Myc and cyclin D1." (PMID 33814008, 2021). "This phenomenon suggests that METTL3 and METTL14 exerted as a complicated regulator in prostate cancer." (PMID 34531875, 2021). "In this study, we found HNRNPA2B1, METTL3, and RBM15B were overexpressed not only in tumor samples but also in high GS prostate cancer patients." (PMID 32710725, 2020). "METTL3 inhibited the expression of LHPP and NKX3‐1 in an m6A‐YTHDF2‐dependent manner to further promote AKT phosphorylation‐induced tumour progression in prostate cancer." (PMID 32808488, 2020). "METTL3 also increases the m6A methylation of lymphoid enhancer-binding factor 1 (LEF1) mRNA, which promotes its protein expression and the progression of prostate cancer by activating the Wnt-β-catenin pathway (Ma, Cao & Zhao, 2020)." (PMID 32765970, 2020). "Prostate cancer cells with FTO knockout were pretreated with CHX and MG-132 for 6 h and then treated with or without 10 ng/ml TGF-β for 48 h, followed by the detection of METTL3 and vimentin expression using western blot analysis." (PMID 38384328, 2024). "Combined with our experimental data and the upregulating of METTL3 by ERK, we assumed that METTL3 and ERK may form a positive feedback loop in prostate cancer, thereby promoting cancer progression." (PMID 37095108, 2023). "Specifically, the silencing of METTL3 conferred by siRNAs or the treatment with the METTL3‐pharmacological inhibitor STM2457 has been shown to significantly alter the transcriptome and splicing patterns regulated by androgens in prostate cancer cells." (PMID 37850412, 2023). "Notably, previous studies have shown that CD81, METTL3, STEAP1, and TRIM28 contributed to the progression of prostate cancer." (PMID 37958805, 2023). "METTL3 positively regulates prostate cancer cell proliferation and metastasis through GLI1 rather than other components of the SHH cascade in an m6A modification-dependent manner, while the underlying mechanism remains to be investigated further." (PMID 37149646, 2023). "In addition, the expression levels of METTL3, FTO (Zhu, Li & Xu, 2021), YTHDF1-2, YTHDC2 were positively correlated with the Gleason score of prostate cancer." (PMID 37701836, 2023). "Furthermore, knockdown of Mettl3 decreased expression of GLI1, a component of the Sonic hedgehog (SHH) signaling pathway, which prostate cancer cells are dependent on for survival." (PMID 35350378, 2022). "Moreover, METTL3 was also found to control the expression of ITGB1, which affects ITGB1 binding to type I collagen and promotes bone metastasis in prostate cancer." (PMID 36360287, 2022). "Studies showed that METTL3 regulates LEF1, KIF3C, USP4, GLI1, ITGB1, IGF1R, and lncRNA PCAT6 expression in an m6A-dependent manner to promote prostate cancer malignant progression." (PMID 35945641, 2022). "In addition, METTL3 also regulates the expression of ITGB1, thus affecting its binding to Collagen I, the mobility of tumour cells, and promoting prostate cancer bone metastasis." (PMID 33461542, 2021). "In addition, methyltransferase-like 3 (METTL3), which is highly expressed in prostate cancer cells, up-regulated integrin β1 transcription under the action of m6A-RNA binding protein human antigen R. The high affinity of integrin β1 and Col I promoted bone metastasis." (PMID 37037822, 2023).
prostate carcinoma (continued). "High levels of METTL3 and CBLL1 could predict the poor prognosis of prostate cancer patients." (PMID 36835633, 2023). "Furthermore, a human prostate cancer xenograft model database analysis (GSE33316, the expression changes after castration of a PDX model) revealed PCa after androgen deprivation exhibited significantly enhanced expression of the METTL3 m6A methyltransferase." (PMID 37095108, 2023). "The role of HNRNPA2B1, METTL3, and RBM15B may play an oncogene in prostate cancer." (PMID 32710725, 2020). "The expression of METTL3, METTL14, WTAP, and CBLL1 was higher in prostate cancer cells compared to non-malignant prostate cells." (PMID 36835633, 2023).